HSPA12B (heat shock protein family A (Hsp70) member 12B)
Synonyms: C20orf60; dJ1009E24.2
Tractability: No criterion of Open Targets' tractability assessment is met for any kind of drug.
Gene: Protein-coding gene on chromosome 20 (3,730,248 to 3,753,553, forward strand). Ensembl gene ENSG00000132622.
Subcellular location (Human Protein Atlas): Nucleoplasm
Pathways (Reactome):
Cellular responses to stimuli: Regulation of HSF1-mediated heat shock response
Gene Ontology:
Molecular function: protein binding
Genetic constraint (gnomAD): Loss-of-function variants: 54 observed, 60.68 expected, observed/expected ratio (o/e) 0.89, 90% interval 0.71 to 1.12. The upper end of that interval is the gene's LOEUF score, 1.12, which puts it in group 4 of 6, group 1 being the genes least tolerant of losing a copy. Missense variants: 929 observed, 900.93 expected, observed/expected ratio (o/e) 1.03, 90% interval 0.98 to 1.09. Synonymous variants: 441 observed, 385.62 expected, observed/expected ratio (o/e) 1.14, 90% interval 1.06 to 1.24.
Homologues: Orthologues: chimpanzee HSPA12B (99% identical), macaque HSPA12B (99% identical), dog HSPA12B (96% identical), guinea pig HSPA12B (96% identical), rat Hspa12b (94% identical), mouse Hspa12b (94% identical), pig HSPA12B (92% identical), rabbit HSPA12B (87% identical), tropical clawed frog hspa12b (74% identical), zebrafish hspa12b (70% identical). Paralogues in human: HSPA12A (62% identical), EEF2K (16% identical), ALPK2 (14% identical), ALPK1 (12% identical).
Diseases named in the same sentence as HSPA12B in open-access papers:
HSPA12B is named in the same sentence as 36 diseases in open-access papers, as found by Europe PMC text mining. Sharing a sentence is not in itself a finding about the gene and the disease. The quoted sentences say what the papers report.
Sepsis (14 papers, 2014 to 2025). Sepsis is defined as life-threatening organ dysfunction caused by a dysregulated host response to infection. "Of greater significance, genetic depletion of HSPA12B in endothelial cells renders mice more susceptible to sepsis-induced downregulation of adhesion molecules and tight junction proteins, vascular hypermutability and multiple organ dysfunction." (PMID 36256626, 2022). "Wild type (WT) and endothelial cell-specific HSPA12B deficient (HSPA12B–/–) mice were subjected to CLP sepsis." (PMID 32457753, 2020). "We observed that endothelial HSPA12B deficiency results increased macrophage infiltration into the heart during CLP sepsis." (PMID 32457753, 2020). "Cecal ligation and puncture sepsis accelerated mortality and caused severe cardiac dysfunction in HSPA12B–/– mice compared with WT septic mice." (PMID 32411123, 2020). "The present study showed that endothelial specific deficiency of HSPA12B (HSPA12B–/–) exhibited increased mortality and worsened cardiac dysfunction in a model of polymicrobial sepsis." (PMID 32457753, 2020). "Our group has uncovered that deficiency of endothelial HSPA12B impairs angiogenesis in a mouse model of myocardial infarction and induces intercellular adhesion molecule 1 and vascular cell adhesion molecule 1 expression in experimental sepsis." (PMID 36256626, 2022). "In the present study, we found that deficiency of HSPA12B in endothelial cells results in more severe cardiac dysfunction, decreased survival outcome, and increased pro-inflammatory cytokine production in polymicrobial sepsis." (PMID 32457753, 2020). "To investigate how EC deficiency of HSPA12B increased adhesion molecule expression and the accumulation of immune cells in the myocardium following polymicrobial sepsis, we examined the effects of serum exosomes isolated from experimental mice on adhesion molecule expression in ECs in vitro." (PMID 32411123, 2020). "Decreased the sepsis-induced upregulation of adhesion molecules and the influx of immune cells such as macrophages and neutrophils in the cardiac muscle of HSPA12B–/– mice." (PMID 39006168, 2024). "More importantly, endothelial exosome-delivered MIR-126 protects from sepsis-induced cardiac dysfunction, a severe clinical manifestation of sepsis-induced organ damage, via regulating HSPA12B function." (PMID 39335561, 2024). "Though both achieved similar AUC, sensitivity and specificity, ApoA5 focuses on ICU mortality of paediatric patients, and HSPA12B focuses on 28-day mortality of patients with severe sepsis." (PMID 37456011, 2023). "The biomarkers, ApoA5 and HSPA12B, which were the only two biomarkers reported their clinical performance, demonstrated consistent significant changes in mouse sepsis with human sepsis." (PMID 37456011, 2023). "This work proposed that miR-126 plays an important role in the Hspa12b regulation of adhesion molecule expression during sepsis; however, the mechanism remains elusive." (PMID 37509546, 2023). "Little is known about the role of HSPA12B in endothelial adherens junction and tight junction and its relationship with lactate in polymicrobial sepsis." (PMID 36256626, 2022). "Next, we induced CLP sepsis in WT, HSPA12B-Tg, and endothelial cell–specific eHSPA12B−/− mice and tested cardiac function 24 h after surgery." (PMID 36256626, 2022). "In conclusion, the findings of this study delineate the essential role of lactate in promoting vascular permeability by downregulating HSPA12B in endothelial cells during sepsis." (PMID 36256626, 2022). "We also observed that administration of supplemental lactate exacerbated sepsis-induced decreases in HSPA12B expression." (PMID 36256626, 2022). "Previous studies have reported that HSPA12B is required to maintain endothelium homeostasis in the mouse model of sepsis and sepsis-induced cardiovascular diseases." (PMID 36256626, 2022).
Sepsis (continued). "We found that administration of lactate or depletion of endothelial cell HSPA12B exacerbates sepsis-induced organ dysfunction and vascular hyperpermeability by impairing VE-cadherin junctions and tight junctions." (PMID 36256626, 2022). "Upregulation of HSPA12B increased levels of miR-126, upregulation of miR-126 reduced levels of dhesion molecules and improved sepsis–induced cardiac dysfunction." (PMID 34956235, 2021). "To elucidate the mechanisms by which endothelial HSPA12B attenuates sepsis induced cardiomyopathy and organ injury, we focused on the role of endothelial HSPA12B in the regulation of macrophage inflammatory response to sepsis." (PMID 32457753, 2020). "Our data provides compelling evidence that endothelial cells can regulate macrophage pro-inflammatory function during sepsis through exosomal HSPA12B." (PMID 32457753, 2020). "The data suggest that endothelial miR-126 plays an important role in HSPA12B regulation of adhesion molecule expression during polymicrobial sepsis." (PMID 32411123, 2020). "The present study demonstrates that endothelial HSPA12B exerts a protective effect on sepsis-induced mortality and cardiomyopathy." (PMID 32457753, 2020). "Our findings suggest that endothelial cell HSPA12B modulates macrophage response to sepsis via exosome secretion which mediates a crosstalk between endothelial cells and macrophages." (PMID 32457753, 2020). "The data suggest that HSPA12B protects against sepsis-induced severe cardiomyopathy via regulating miR-126 expression which targets adhesion molecules, thus decreasing the accumulation of immune cells in the myocardium." (PMID 32411123, 2020). "Wild-type (WT) and endothelial HSPA12B knockout (HSPA12B–/–) mice were subjected to polymicrobial sepsis induced by cecal ligation and puncture (CLP)." (PMID 32411123, 2020). "This study investigated the mechanisms by which endothelial HSPA12B protects polymicrobial sepsis–induced cardiomyopathy." (PMID 32411123, 2020). "The present study has shown that endothelial-specific HSPA12B exerts a protective effect on sepsis-induced cardiomyopathy." (PMID 32411123, 2020). "Our observation is consistent with previous studies showing HSPA12B is essential for EC functioning during sepsis/septic shock." (PMID 32411123, 2020). "To further investigate the role HSPA12B in the regulation of adhesion molecule expression during polymicrobial sepsis, we performed in vitro experiments." (PMID 32411123, 2020). "Of greater importance, endothelial HSPA12B exerts an anti-inflammatory effect on macrophages in response to sepsis." (PMID 32457753, 2020). "The data indicate that EC HSPA12B plays a role in the regulation of NF-κB activation and proinflammatory cytokine production during polymicrobial sepsis." (PMID 32411123, 2020). "Several endothelium-related molecules such as angiopoietins, vWF and sICAM-1 were demonstrated to be correlated with severity of sepsis, and similarly, HSPA12B, mainly located in endothelial cells, was considered as a predictor for prognosis of severe sepsis." (PMID 24977412, 2014). "In addition, heat shock protein 72 (HSP72), heat shock protein 20 (HSP20), and heat shock protein A12B (HSPA12B) are beneficial in the management of myocardial injury in patients with sepsis." (PMID 40041174, 2025). "Plasma HSPA12B was elevated in both septic mice and patients, indicating that HSPA12B may be a good predictor of poor prognosis in patients with severe sepsis." (PMID 39983811, 2025). "Conversely, endothelial HSPA12B knockout exacerbated sepsis-induced cardiac dysfunction." (PMID 39983811, 2025). "Zhang’s results has suggested that managing Hspa12b expression could provide therapeutic benefits, particularly in sepsis-induced ALI48." (PMID 41213982, 2025). "Interestingly, Hspa12b−/− mice show low levels of miR-126 upon LPS sepsis induction and suffer from aggravated cardiac dysfunction after sepsis induction." (PMID 37509546, 2023).
Sepsis (continued). "Moreover, serum AST and creatinine levels were higher in eHSPA12B−/− CLP mice than in WT CLP mice, suggesting that inhibition of HSPA12B worsens liver and kidney injury after sepsis." (PMID 36256626, 2022). "We found that the expression of HSPA12B in the heart decreased remarkably after CLP sepsis." (PMID 36256626, 2022). "Interestingly, treatment with supplemental lactate further downregulated HSPA12B expression following sepsis." (PMID 36256626, 2022). "In addition, inhibition of lactate signaling reverses HSPA12B expression and improves vascular integrity after sepsis." (PMID 36256626, 2022). "Importantly, pharmacological inhibition of lactate/GPR81 signaling attenuated sepsis-induced HSPA12B downregulation and vascular permeability and improved survival outcome of septic mice." (PMID 36256626, 2022). "In addition, pharmacologically inhibiting the lactate receptor, GPR81, attenuated sepsis-induced decreases in HSPA12B expression, vascular permeability, and improved survival outcome of septic mice." (PMID 36256626, 2022). "Endothelial cell–specific deletion of HSPA12B exhibited vascular hyperpermeability via downregulation of VE-cadherin and tight junction protein levels and worsened multiple organ dysfunction during polymicrobial sepsis." (PMID 36256626, 2022). "Administration of 3OBA enhanced HSPA12B expression in the presence of sepsis." (PMID 36256626, 2022). "It would be interesting to investigate whether endothelial HSPA12B could regulate macrophage inflammatory responses during sepsis." (PMID 32457753, 2020). "The data suggests that endothelial HSPA12B plays a role in limiting mortality in CLP sepsis." (PMID 32457753, 2020). "Importantly, delivery of exosomes loaded with miR-126 attenuated sepsis-induced expression of adhesion molecules and accumulation of macrophages and neutrophils in the myocardium of HSPA12B–/– mice." (PMID 32411123, 2020). "The present study investigated whether endothelial HSPA12B could regulate macrophage pro-inflammatory response during sepsis." (PMID 32457753, 2020). "The data suggests that endothelial HSPA12B could play an important role in the protection against sepsis induced organ injury." (PMID 32457753, 2020). "To elucidate the mechanisms by which endothelial HSPA12B regulates macrophage pro-inflammatory response during polymicrobial sepsis, we examined whether HSPA12B is released through exosome secretion." (PMID 32457753, 2020). "The data indicate that EC HSPA12B could attenuate infiltration of immune cells into the myocardium during polymicrobial sepsis." (PMID 32411123, 2020). "First, deficiency of endothelial-specific HSPA12B (HSPA12B–/–) results in severe cardiac dysfunction and poor survival outcome following polymicrobial sepsis, suggesting that endothelial HSP12B serves a protective role in cardiac function in sepsis." (PMID 32411123, 2020). "Importantly, endothelial exosomal HSPA12B downregulates macrophage pro-inflammatory responses in sepsis." (PMID 32457753, 2020). "The data suggest that HSPA12B may prevent upregulation of adhesion molecule expression in ECs during sepsis." (PMID 32411123, 2020). "Endothelial HSPA12B also protects vascular endothelial cells from sepsis induced acute lung injury." (PMID 32457753, 2020). "We then addressed whether HSPA12B participates in vascular permeability following sepsis." (PMID 36256626, 2022). "In addition, we observed that pro-inflammatory cytokine levels in HSPA12B–/– septic mice were markedly greater than in WT septic mice, suggesting that endothelial HSPA12B also plays a role in regulating macrophage pro-inflammatory responses during sepsis." (PMID 32457753, 2020). "This suggests that endothelial HSPA12B may play a role in not only regulating adhesion molecule expression but also controlling NF-κB mediated inflammatory cytokine production in polymicrobial sepsis." (PMID 32411123, 2020).
Sepsis (continued). "We demonstrated that EC HSPA12B could regulate miR-126 expression, which targets adhesion molecules, resulting in decreases in the accumulation of immune cells in the myocardium, thus attenuating sepsis-induced cardiac dysfunction." (PMID 32411123, 2020). "The data indicates that endothelial cell HSPA12B could play a role in the attenuation of macrophage infiltration into the myocardium through suppressing myocardial adhesion molecule expression during sepsis." (PMID 32457753, 2020). "This indicates that HSPA12B is involved in controlling adhesion molecule expression and immune cell infiltration into the myocardium following CLP sepsis." (PMID 32411123, 2020). "However, the mechanisms by which HSPA12B preserves EC function during sepsis are still unknown." (PMID 32411123, 2020). "In the discovery of HSPA12B and TREM-1, besides measuring the changes of candidate biomarkers in mouse sepsis, the disease severity of mouse sepsis, either controlled by the CLP puncture numbers or monitored by bacterial loads, was used to analyse the correlation with candidate biomarkers." (PMID 37456011, 2023). "CLP sepsis markedly increased the levels of miR-126 in exosomes from WT mice but not from HSPA12B–/– mice." (PMID 32411123, 2020). "We examined whether endothelial HSPA12B could regulate monocyte/macrophage populations in spleen and circulation after induction of CLP sepsis." (PMID 32457753, 2020). "Subsequently, in a prospective study on patients with severe sepsis from ICU (40 survivors and 26 non-survivors), ELISA was used to measure plasma HSPA12B levels." (PMID 37456011, 2023).
myocardial infarction (7 papers, 2016 to 2025). Gross necrosis of the myocardium, as a result of interruption of the blood supply to the area, as in coronary thrombosis. "Endothelial HSPA12B has been reported to attenuate endotoxemia and cardiac injury due to myocardial infarction." (PMID 32457753, 2020). "Heat shock protein A12B (HSPA12B) is predominately expressed in endothelial cells (ECs) and has been reported to protect against cardiac dysfunction from endotoxemia or myocardial infarction." (PMID 32411123, 2020). "We then examined the effects of HSPA12B on I/R-induced myocardial infarction." (PMID 27644317, 2016).
cardiomyopathy (5 papers, 2020 to 2025). A disease of the heart muscle or myocardium proper. "We previously reported that transgenic mice with endothelial cell-specific overexpression of HSPA12B protect against endotoxin-induced cardiomyopathy via activation of PI3K signaling." (PMID 40443679, 2025).
lung carcinoma (3 papers, 2015 to 2021). "Collectively, HSPA12B is a facilitator of lung cancer-associated angiogenesis." (PMID 25909170, 2015). "The present study identified HSPA12B as a novel facilitator of lung tumor growth and a potential therapeutic target for the treatment of lung cancer." (PMID 25909170, 2015). "In the present study, we showed that HSPA12B in pulmonary endothelial cells stimulated lung cancer growth in mice by enhancing angiogenesis, increasing cell proliferation, and suppressing apoptosis in tumors via a Cox-2-dependent mechanism." (PMID 25909170, 2015). "Further studies are needed to investigate whether targeted suppressing HSPA12B would limit the growth and progression of lung cancer." (PMID 25909170, 2015). "The present study identified HSPA12B as a novel facilitator of lung tumor growth, which suggests that targeting HSPA12B could be a therapeutic strategy for the treatment of lung cancer." (PMID 25909170, 2015). "To investigate the roles of HSPA12B in lung cancer progression, we generated HSPA12B Tg mice." (PMID 25909170, 2015). "Our data indicates that HSPA12B could be an alternative therapeutic target for the suppression of lung cancer progression." (PMID 25909170, 2015). "However, whether HSPA12B participates in lung cancer growth is unknown." (PMID 25909170, 2015).
asthma (2 papers, 2015 to 2016). "Interestingly, within MZ2 siblings we identified a blood eDMR comprising 37 significant eDMCs within a CpG island overlapping the HSPA12B locus reported to be involved in asthma with interaction of environmental tobacco smoke." (PMID 26699896, 2015).
breast carcinoma (2 papers, 2018 to 2021). "HSPA12B mRNA was down-regulated in lung squamous cell carcinoma, lung adenocarcinoma, breast cancer, uterine corpus endometrial carcinoma and kidney renal papillary cell carcinoma." (PMID 34712697, 2021). "Another interesting observation from the present study is that several HSPs were downregulated in all breast cancer subtypes: DNAJB4, DNAJC18, HSPA12A, HSPA12B, HSPB2, HSPB6, and HSPB7." (PMID 29954368, 2018).
ischaemic stroke (2 papers, 2015 to 2018). "Here, we demonstrated that in the late phase of ischaemic stroke, HSPA12B improved functional recovery through an eNOS‐dependent mechanism." (PMID 29411514, 2018). "In this study, we revealed that ischaemic stroke up‐regulated HSPA12B expression and this up‐regulation prolonged at least to 7 days post‐stroke." (PMID 29411514, 2018). "In summary, HSPA12B overexpression promoted mice survival and functional recovery at chronic phase of ischaemic stroke." (PMID 29411514, 2018). "We demonstrate for the first time that overexpression of HSPA12B promoted neurological function recovery and improved survival at chronic phase of ischaemic stroke." (PMID 29411514, 2018). "The data suggest that targeting HSPA12B expression could serve as a potential target for the management of functional disability after ischaemic stroke." (PMID 29411514, 2018). "Importantly, administration with eNOS inhibitor L‐NAME diminished the protection of HSPA12B in mice survival and neurologic function recovery post‐stroke, suggesting that eNOS‐mediated neuroprotective effects of HSPA12B at chronic phase of ischaemic stroke." (PMID 29411514, 2018). "Thus, HSPA12B was up‐regulated in a prolonged manner after ischaemic stroke." (PMID 29411514, 2018). "HSPA12B was validated as a target of miR-134, and increased expression of HSPA12B correlated with attenuation of neural cell damage in OGD-treated N2A cells, and reduced infarct size and improved neurological outcomes in mice with ischemic stroke." (PMID 25821444, 2015).
age (1 paper, 2025). A temporal measurement of the time period elapsed since an identifiable point in the life cycle of an organism. "HSPA12B thus serves as a critical regulator of endothelial senescence and emerges as a potential therapeutic target for preventing age‐related cardiovascular disease." (PMID 41063400, 2025).